CNN1 (calponin 1)
Diseases named in the same sentence as CNN1 in open-access papers (continued):
Sharing a sentence is not in itself a finding about the gene and the disease.
adenomyosis (1 paper, 2025). The growth of endometrial tissue inside the muscular wall of the uterine corpus. "Deconvolution of bulk RNA‐seq data of adenomyosis stromal cells showed a higher proportion of CNN1+ stromal ecotypes within the AM group." (PMID 40190183, 2025). "Given the robust correlation between stromal ecotypes in Visium data and stromal cells in single‐cell data, we posited that CNN1+ stromal fibroblasts played a major role in adenomyosis fibrogenesis." (PMID 40190183, 2025). "CNN1+ stromal fibroblasts performed a crucial role in adenomyosis fibrogenesis." (PMID 40190183, 2025).
angioleiomyoma (1 paper, 2025). A benign, slow-growing neoplasm that arises from the dermis or subcutaneous tissue. "Angioleiomyoma has been observed to show strong immunoreactivity and stains diffusely for SMA, calponin (CNN1), and caldesmon." (PMID 39051589, 2025).
arterial disease (1 paper, 2022). "The aberrant methylation in the promoter region of MYH11 and CNN1 genes, two hyper-down hub genes screened in our study, was found to be associated with VSMCs differentiation in arterial disease." (PMID 36292702, 2022).
breast adenocarcinoma (1 paper, 2020). "Finally, IDC cell lines (MCF-7 and T47D), TNBC cell line (MDA-MB-231), and breast adenocarcinoma cell line (CAMA-1) were chosen, and auxiliary qRT-PCR was conducted to detect the expression of CNN1 and STAT1 in those cell lines." (PMID 31986487, 2020).
cardiomyopathy (1 paper, 2014). A disease of the heart muscle or myocardium proper. "Inhibition of CNN1 expression may disrupt its suppression of cardiomyopathy through the εPKC pathway." (PMID 25338953, 2014).
clear cell carcinoma (1 paper, 2017). "Interestingly, although CNN1 overexpression caused a suppression of anoikis survival and ip tumorigenesis in transformed FTE cells, the same re-expression in clear cell carcinoma-like SKOV3 cells had no changes of either phenotype." (PMID 28977852, 2017). "However, unlike the case in the transformed fimbrial cells, neither anoikis resistance nor i.p. tumorigenesis was altered in this clear-cell carcinoma like cell line with CNN1 overexpression." (PMID 28977852, 2017).
congenital glaucoma (1 paper, 2024). "The gene ontologies for list 7+ linked the non-overlapping genes CDC42EP2, CLDN5, CNN1, DES, KCNMB1, and MYH11 to Congenital Glaucoma." (PMID 39480826, 2024).
Ehlers-Danlos syndrome (1 paper, 2024). The Ehlers–Danlos syndromes (EDS) are a clinically and genetically heterogeneous group of heritable connective tissue disorders (HCTDs) characterized by joint hypermobility, skin hyperextensibility, and tissue fragility. "The gene ontologies for list 8+ linked CDC42EP2, FOXF1, SGCA, and SORBS1 to Megacystis-Microcolon-Intestinal Hypoperistalsis Syndrome while CDC42EP2 and CNN1 linked to Classical-like Ehlers-Danlos Syndrome." (PMID 39480826, 2024). "No direct link between CNN1 or CDC42EP2 could be made with TNXB or Classical-like Ehlers-Danlos Syndrome (cEDS) through a literature search." (PMID 39480826, 2024).
Ehlers-Danlos syndrome type 1 (1 paper, 2024). "We propose that CNN1 is a novel gene in Classical-like Ehlers-Danlos Syndrome type 1." (PMID 39480826, 2024).
Era (1 paper, 2025). "The protein expression levels of calponin-1, SM22α, and αSMA, and the mRNA expression levels of calponin-1, αSMA, SM-MHC, SOD, and CAT in the Era-induced group were significantly downregulated compared to those in the NC group." (PMID 39754271, 2025).
Esophageal stricture (1 paper, 2023). A pathological narrowing of the esophagus that is caused by the development of a ring of scar tissue that constricts the esophageal lumen. "Compared with those in the control group, esophageal stricture was significantly reduced in the PGA + bFGF group, and the areas stained with α-SMA and calponin-1 antibodies were significantly inhibited in the PGA + bFGF and PGA groups." (PMID 37635203, 2023).
gastric adenocarcinoma (1 paper, 2023). "During this research, we noted a significant increase in CNN1 expression in paraneoplastic tissue of gastric adenocarcinoma." (PMID 37153789, 2023). "In the prognostic analysis, we also found that in gastric adenocarcinoma, the prognosis of the CNN1 low-expression group was better than that of the high-expression group." (PMID 37153789, 2023). "High levels of CNN1 indicate a poor prognosis for 11 tumors, which include stomach adenocarcinoma (STAD)." (PMID 37153789, 2023). "Furthermore, in the comparison of tumor stages of gastric adenocarcinoma, CNN1 expression was higher in advanced gastric adenocarcinoma than in early-stage gastric adenocarcinoma." (PMID 37153789, 2023). "This non-linear expression of CNN1 in precancerous tissues or early tumor tissue is particularly evident in gastric adenocarcinoma." (PMID 37153789, 2023).
glaucoma (1 paper, 2024). Increased pressure in the eyeball due to obstruction of the outflow of aqueous humor. "The literature did not reveal any previous association between CNN1 (calponin 1) and glaucoma, however, TGF-β1 promotes CNN1 expression and CNN1 has been identified in the trabecular meshwork." (PMID 39480826, 2024). "We propose that CNN1, and DES are novel genes in Congenital Glaucoma." (PMID 39480826, 2024).
in situ ductal carcinoma (1 paper, 2023). "Reduced MEC differentiation measured by a decrease in expression of Cnn1 and Acta2 also precedes the progression of in situ ductal carcinoma to invasive disease in mammary gland; thus, the clinical impact of targeting MEC differentiation may expand beyond SG regeneration." (PMID 36966175, 2023).
invasive breast carcinoma (1 paper, 2020). A carcinoma that infiltrates the breast parenchyma. "The gene expressions of ACOT7, STAT1, TYMP, and VOPP1 were significantly increased in invasive breast carcinoma, while the gene expressions of ACTG2, CNN1, CDC14B, NFIB, RCN1, and TRIM2 were dramatically downregulated in BRCA." (PMID 31986487, 2020).
invasive carcinoma (1 paper, 2017). A carcinoma that is not confined to the epithelium, and has spread to the surrounding stroma. "Thus, CNN1 down-regulation may be more important in the development of HGSC than cl cell carcinoma of the ovarian which is known to transform from benign, borderline malignancy to invasive carcinoma." (PMID 28977852, 2017).
leiomyoma (1 paper, 2025). A well-circumscribed benign smooth muscle neoplasm characterized by the presence of spindle cells with cigar-shaped nuclei, interlacing fascicles, and a whorled pattern. "DEX-treatment reduced LAMA2 and increased CNN1 levels (coding for extracellular matrix and smooth muscle proteins, respectively) in FKBP5-silenced vs scramble siRNA-transfected leiomyoma cultures." (PMID 40290045, 2025).
leukemia (1 paper, 2022). A malignant (clonal) hematologic disorder, involving hematopoietic stem cells and characterized by the presence of primitive or atypical myeloid or lymphoid cells in the bone marrow and the blood. "In fact, CNN1 caused pronounced rupture in membrane integrity on leukemia cells compared to IM standard therapy." (PMID 35897681, 2022). "In the current study, CNN1 caused depolarization of mitochondrial membrane potential in both leukemia cell lines and was more pronounced when compared to IM (p < 0.001)." (PMID 35897681, 2022). "In addition, CNN1 also induced genotoxic effects and caused DNA fragmentation, cell cycle arrest at the G2/M phase in leukemia cells." (PMID 35897681, 2022). "Previously, Portilho and co-workers demonstrated that CNN1 has excellent cytotoxicity against different leukemia cells, after 72 h of treatment." (PMID 35897681, 2022). "In this scenario, our finding suggests that CNN1 induces apoptosis in resistant leukemia cells by inducing DNA damage throughout H2AFX modulation." (PMID 35897681, 2022). "The results demonstrate that CNN1 was able to induce apoptosis, cell membrane rupture and mitochondrial membrane depolarization in leukemia cell lines." (PMID 35897681, 2022). "Data from previous work by our group showed that CNN1 reduced TOP1 expression levels in both leukemia cell lines." (PMID 35897681, 2022). "Therefore, CNN1 presented anticancer properties against leukemia multidrug resistant cell line being a potential anticancer agent for the treatment of resistant CML." (PMID 35897681, 2022). "Therefore, the aim of the study was to examine the pharmacological role of CNN1, a para-naphthoquinone, in a leukemia multidrug resistant cell line." (PMID 35897681, 2022). "It was also investigated whether the pronounced effect of CNN1 on leukemia multidrug resistant cell line could reflect a cell cycle arrest." (PMID 35897681, 2022). "Moreover, it was observed that CNN1 is less toxic to normal human cells such as fibroblasts (IC50 15.34 μM) when compared to leukemia cell lines." (PMID 35897681, 2022). "Therefore, this study aimed to examine whether CNN1 is able to circumscribe the multidrug resistant and induce cell death in resistant leukemia cells." (PMID 35897681, 2022). "The comet assay was performed to determine genotoxic potential of CNN1 (0.1 μM) and IM (0.1 μM) in K-562 and FEPS leukemia cell lines and PBMC after 3 h of exposure." (PMID 35897681, 2022). "Statistical analysis showed that CNN1 was more genotoxic to leukemia cells than to non-malignant peripheral mononuclear blood cells (PBMC)." (PMID 35897681, 2022). "Our results indicate the hypothesis that CNN1 induces overexpression of H2AFX in K-562 (p < 0.01) and FEPS (p < 0.01) cells, suggesting that this upregulation of H2AFX gene has a major role in initiating cell death in leukemia MDR cells through the DNA damage signaling pathway." (PMID 35897681, 2022).
melanoma (1 paper, 2017). A malignant, usually aggressive tumor composed of atypical, neoplastic melanocytes. "In CNN1-null transgenic mice receiving intravenous or intraperitoneal injection of B16 melanoma cells, a more extensive metastasis occurred in the lung and in the peritoneal cavity." (PMID 28977852, 2017).
Obesity (1 paper, 2020). Accumulation of substantial excess body fat. "When comparing both timepoints, most transcripts exhibited a different expression pattern, including Muc15, Cnn1, and Acta2 which were not affected by obesity at E13." (PMID 32203108, 2020).
paraganglioma (1 paper, 2023). A benign or malignant neoplasm arising from paraganglia located along the sympathetic or parasympathetic nerves. "It is noteworthy that in BRCA, pheochromocytoma and paraganglioma (PCPG), and SARC, patients in the CNN1 high-expression group had better OS than those in the CNN1 low-expression group (p < 0.05)." (PMID 37153789, 2023).
pulmonary hypertension (1 paper, 2024). Increased pressure within the pulmonary circulation due to lung or heart disorder. "CNN1 and TAGLN with ACTA2 were implicated in Smooth Muscle Cell Dysfunction in Pulmonary Hypertension (q = 2.622x10-3)." (PMID 39480826, 2024).
uterine corpus endometrial carcinoma (1 paper, 2023). A endometrial carcinoma (disease) that involves the body of uterus. "Patients in the CNN1 high-expression group of uterine corpus endometrial carcinoma had better RFS than those in the CNN1 low-expression group (p < 0.05)." (PMID 37153789, 2023).
uterine leiomyosarcoma (1 paper, 2017). "In addition, CNN1 was downregulated in uterine leiomyosarcoma and may play a role as a tumor suppressor." (PMID 28977852, 2017).
tumor (33 papers, 2007 to 2026). "CNN1 is also required for the maturation of tumor vessels, and its loss in host mural cells would inhibit this process." (PMID 37153789, 2023). "In summary, five candidate genes (TIMP1, SPARCL1, MYL9, TPM2, and CNN1) were finally characterized as the hub gene associated with tumor recurrence in CRC." (PMID 33897765, 2021). "In this study, CNN1 was identified by bioinformatics analysis, which was associated with the prognostic and tumor stage." (PMID 31986487, 2020). "Tumour vasculature has an immature phenotype characterised by incomplete pericyte coverage, irregular shapes and growth patterns, and permeable membranes, which may in part be due to CNN1 loss." (PMID 35842572, 2022). "In vivo, CNN1 overexpression counteracted the tumor-suppressive effects of lactate inhibition, restoring tumor growth and autophagy levels." (PMID 42129130, 2026). "For example, cells in immune_2 and immune_1 are surrounded by tumor cells and stroma cells, respectively, and have distinct expression patterns of marker genes such as CNN1, DES, and TMEFF2." (PMID 39960663, 2025). "Such dedifferentiated PSMC (dPSMC) were apparent within strands of stromal tissue between tumour glands with disorganised isolated PSMC displaying decreased CNN1, CCDC102B and MCAM immunopositivity." (PMID 41378308, 2025). "They reported decreased CNN1 expression in tumor tissues compared to adjacent normal tissues, correlating with poor OS in patients." (PMID 39284282, 2024). "The qPCR analysis was performed to examine the expression levels of MEG3, miR-330, and CNN1 in tumor tissues and cells." (PMID 38240701, 2024). "Results showed that miR-330 was significantly upregulated (P < 0.05), whereas MEG3 (P < 0.05) and CNN1 (P < 0.01) were significantly downregulated in tumor tissues compared to paratumor tissue at the RNA level." (PMID 38240701, 2024). "CNN1 inhibits tumor cell proliferation and migration probably by stabilizing the cytoskeleton and making intercellular junctions tighter." (PMID 37153789, 2023). "High tumor stiffness is closely related to tumor progression and can drive invasion by modulating the CNN1/β-catenin/N-cadherin pathway, contributing to the binding of cancer cells to blood vessels." (PMID 37762011, 2023). "To analyze the effect of high versus low expression of CNN1 on tumor prognosis, we performed a pan-cancer survival analysis using the PrognoScan, Kaplan–Meier plotter, and GEPIA databases." (PMID 37153789, 2023). "It has been documented that CNN1 can inhibit tumor cell formation, proliferation, and colony formation as a tumor suppressor." (PMID 37251946, 2023). "Xenograft tumor model with CNN1 revealed overtly lowered in tumor volume and weight relative to mice vector xenograft tumor model." (PMID 35903683, 2022). "Nude mouse tumor tissues were used for immunohistochemical experiments to detect the expression levels of Ki-67 and CNN1." (PMID 35903683, 2022). "BC cells overexpressing CNN1 were utilized to establish a nude mouse xenograft tumor model, and the tumor volume and tumor weight were detected." (PMID 35903683, 2022). "In order to research the relationship between CNN1 and BC in vivo, subcutaneous xenograft tumor model in nude mice was built." (PMID 35903683, 2022). "Nude mouse tumor tissues were used for immunohistochemical experiments to test the expression levels of Ki-67 and CNN1." (PMID 35903683, 2022). "Together, these results demonstrate that factors like TGF-β1 are secreted by HCT8 tumour cells and that calponin 1 induction requires Alk5 S/T kinase activity." (PMID 31409840, 2019). "Previous studies have revealed an antimetastatic role of CNN1 in both the tumor aspect and the recipient aspects." (PMID 28977852, 2017). "In summary, this study reveals a tumor suppressor function of CNN1 in the development of ovarian HGSC from fallopian tube fimbriae." (PMID 28977852, 2017).
tumor (continued). "We discovered a tumor suppressor role of CNN1 that must be downregulated to encourage cell exfoliation, migration, anchorage-independent growth (AIG), and tumorigenesis." (PMID 28977852, 2017). "The study disclosed multiple tumor suppressor roles of CNN1 in the development of HGSC from the fallopian tube, and loss of CNN1 expression is crucial for its metastasis to a new site." (PMID 28977852, 2017). "To study the tumor suppressor function of CNN1, we cloned the gene into the pEGFP-C1 vector and transfected to the nonexpressing FE-RAS cells." (PMID 28977852, 2017). "Pericyte-specific expression of pMLC and CNN1 in untreated tumor pericytes was low." (PMID 40140727, 2025). "Moreover, vessel normalization in Rgs5KO mice was associated with increased expression of the contractile marker CNN1 in tumor pericytes, whereas vascular expression of the synthetic marker collagen I (COLI) was reduced." (PMID 39286984, 2024). "However, a high level of CNN1 promotes anoxia and angiogenesis in the tumor microenvironment, which increase the degree of tumor malignancy." (PMID 37153789, 2023). "CNN1 was found to trigger the growth of “leaky” tumor vessels." (PMID 37153789, 2023). "In conclusion, our results show that CNN1 plays multiple roles in tumor angiogenesis and the immune checkpoint by contributing to the progression of and poor prognosis in various cancers, thus providing a promising candidate for pan-cancer prognosis and immunotherapy." (PMID 37153789, 2023). "Fourth, although we have confirmed the great potential of CNN1 in pan-cancer immunotherapy, both inhibition and overexpression of CNN1 were found to be relevant in different tumors; therefore, more research has to be done to implement the use or targeting of CNN1 in tumor immunotherapy." (PMID 37153789, 2023). "Then we observed that CNN1 expression was reduced in tumor tissues and cells." (PMID 31986487, 2020). "The downregulation of CNN1 in malignant transformation was also observed in clinical specimens in which HGSC tumor tissues from both the ovary and the fallopian tube had a lower expression level than did those from the normal ovary, normal fallopian tube, and fallopian tube epithelial scrapings." (PMID 28977852, 2017). "In addition, genes involved in cell differentiation and apoptosis (PDZK1) and genes encoding actin and actin-binding proteins (CNN1, ACTA2) were also downregulated in both types of tumor cells." (PMID 17389037, 2007). "However, previous studies have suggested that CNN1 was found to be elevated in tumor tissues, at least those such as LUSC, OV, LIHC, and BLCA; thus, it might be considered a potential oncogene to be involved in cancer progression." (PMID 37153789, 2023). "The specific mechanisms involved have to be further investigated, but CNN1 certainly plays a role in the development of most tumors, and this role may be played throughout the stages of tumor development, including through the pre, early, and advanced cancer stages." (PMID 37153789, 2023). "Moreover, CNN1 displays tumor-suppressive properties in human uterine leiomyosarcoma." (PMID 37153789, 2023). "The results suggest that CNN1 has a crucial role in angiogenesis and maturation, and CNN1 expression is correlated with the stability of the tumor cytoskeleton, which also influences the migration of tumor cells and the formation of distal lesions together with VEGFA." (PMID 37153789, 2023). "However, CNN1 again showed an increasing trend during tumor development." (PMID 37153789, 2023). "Whether CNN1 is an oncogene like CNN2 or a tumor suppressor gene in breast remains unknown." (PMID 31986487, 2020).